CUBN (cubilin)
Diseases named in the same sentence as CUBN in open-access papers (continued):
Sharing a sentence is not in itself a finding about the gene and the disease.
chronic kidney disease (7 papers, 2012 to 2023). Impairment of the renal function secondary to chronic kidney damage persisting for three or more months. "It has been suggested that the tubular albuminuria observed in presence of C-terminal variants in CUBN has a benign or even slightly protective effect on kidney function in chronic kidney disease if glomerular albuminuria is also present." (PMID 36926036, 2023). "As albuminuria is an established risk factor for progressive renal function loss, the GWAS findings raised the hypothesis that genetic variation in the CUBN locus could be associated with progressive renal function loss and finally end stage renal disease." (PMID 22574174, 2012). "The demonstration of a CUBN-focused GRS in relation to albuminuria and eGFRcreatinine further suggests an important role of CUBN-variants in the future personalization of chronic kidney disease management." (PMID 36926036, 2023). "CUBN, UMOD, and SHROOM3 were identified by human GWAS as being associated with albuminuria, kidney function, and chronic kidney disease (CKD)." (PMID 26219736, 2015). "Among the proteins in the predictive list are CUBN, IGHG1, CERU, TFRE and A2GL, which are urinary glycoproteins associated with chronic kidney disease." (PMID 25182141, 2014). "Cubilin and megalin are responsible for reabsorbing transferrin iron in the kidney urine collecting system and the influence of CUBN on chronic kidney disease in African Americans has been studied." (PMID 22761678, 2012). "As albuminuria is a risk factor for progression of CKD up to end stage renal disease (ESRD), we hypothesized that genetic variation in CUBN is associated with development of ESRD." (PMID 22574174, 2012).
renal cell carcinoma (5 papers, 2017 to 2025). "Interestingly, a low expression of CUBN in renal cell carcinoma is significantly associated with early disease progression and poor patient outcomes." (PMID 40001939, 2025). "However, cubilin (CUBN) has been identified and validated as a marker capable of classifying renal cell carcinoma (RCC) patients into low- and high-risk groups." (PMID 38530585, 2024). "CUBN is an endocytic receptor expressed in the epithelium of the intestines and kidneys and is downregulated in renal cell carcinoma." (PMID 40001939, 2025). "We used the TCGA dataset of renal cell carcinoma patients and generated Kaplan-Meier analyses for the two most deregulated transcripts (CUBN and KRT17) as well as for the identified miRNA target genes." (PMID 31878355, 2019). "In addition, links have been found between CUBN and the development and progression of cancers, such as gastric cancer, breast cancer, renal cell carcinoma, and colorectal cancer." (PMID 36583005, 2022).
type 1 diabetes (5 papers, 2015 to 2020). "A missense variant (I2984V) in the cubilin gene CUBN was associated with a 41% increased risk for development of persistent MA during 20 years of follow-up among 1304 participants with type 1 diabetes in a prospective study." (PMID 26465605, 2015). "The CKDGen consortium meta-analysis identified a missense SNP in CUBN (rs18801239) associated with urinary albumin/creatinine ratio and clinical microalbuminuria in the general population, an association replicated in an AA cohort with type 1 diabetes and later in the Framingham Offspring Study." (PMID 32379818, 2020). "The goal of this work was to determine if type 1 diabetes induces low expression of megalin, cubilin, ClC‐5, and CFTR in renal tissues and if this fact is associated with the microalbuminuria and LMW proteinuria observed in DN disease." (PMID 28676554, 2017). "The goal of this work was to evaluate renal function and the expression of megalin, cubilin, CFTR (cystic fibrosis transmembrane conductance regulator), and ClC‐5 in the proximal tubule and renal cortex of rats with type 1 diabetes." (PMID 28676554, 2017). "However, our main finding, the association of the CUBN rare variant with albuminuria, remains unaffected as the meta-analysis for this variant only included type 2 diabetes cohorts because of the lack of genotyping or poor imputation quality in type 1 diabetes replication cohorts." (PMID 30547231, 2019).
breast carcinoma (4 papers, 2020 to 2025). "The rs12357285 SNP at 10p13, is an intronic variant in CUBN and was associated with MD in our discovery dataset and European women, but not validated in our dataset of unaffected breasts in breast cancer cases." (PMID 41272850, 2025). "Both genes do not seem to have direct associations with breast cancer: COL16A1 encodes the alpha chain of type XVI collagen; CUBN encodes a protein called cubilin, which is involved in the uptake of vitamin B12 from food into the body." (PMID 35321091, 2021).
COVID-19 (4 papers, 2022 to 2024). A disease caused by infection with severe acute respiratory syndrome coronavirus 2. "Vitamin D deficiency has been associated with COVID-19 severity and outcome; therefore, the possible involvement of Megalin and Cubilin deserves further investigation." (PMID 36830041, 2023). "We successfully identified the shared 6 candidate gene signatures (RRM2, EGF, TMEM252, RARRES1, COL6A3, CUBN) between COVID-19 and AKI." (PMID 37789254, 2023). "The results revealed that 6 key gene signatures (RRM2, EGF, TMEM252, RARRES1, COL6A3, CUBN) were recognized to have great influences on COVID-19 and AKI." (PMID 37789254, 2023). "Furthermore, the concentration of CUBN, an important regulator in tubular reabsorption, was found to be decreased in the urine of patients with severe COVID-19, indicating a potential dysregulation of reabsorption." (PMID 38510452, 2024). "The relationship between antibodies to ORP150 and CUBN and the severity of COVID-19 remains unclear in the available literature." (PMID 38510452, 2024). "The following proteins have sparked interest in COVID-19 patients: XPNPEP2, HCII, ORP150, CREB3L3, APOA1, and CUBN." (PMID 38510452, 2024). "The study found that the levels of two important regulators involved in renal tubular reabsorption, megalin (LRP2) and cubilin (CUBN), showed a decreasing trend in the urine of patients with COVID-19." (PMID 36203586, 2022).
cystinosis (4 papers, 2019 to 2025). Cystinosis is a metabolic disease characterized by an accumulation of cystine inside the lysosomes, causing damage in different organs and tissues, particularly in the kidneys and eyes. "Therefore, abnormal NHE3 trafficking to the brush border in cystinosis models could also help explain the loss of megalin and cubilin, accounting for the overall water, small proteins and solute loss associated with the renal FS." (PMID 39990449, 2025). "Proximal tubule cells (PTCs) are the most affected cells in cystinosis and are characterized by the accumulation of cystine crystals, as well as by PTC de-differentiation accompanied by loss of the endocytic receptors megalin and cubilin." (PMID 30774622, 2019). "Besides CLCN5 (DD1) and OCRL (Lowe syndrome and Dent disease type 2) genes, they include LRP2 (DB/FOAR), CUBN, AMN (Imerslund–Gräsbeck syndrome), and CTNS (nephropathic cystinosis)." (PMID 31947599, 2020). "Notably, the effect was more pronounced for CUBN and AQP1 in cystinotic cells, suggesting that DNA methylation plays a key role in repressing these transporters in cystinosis and that demethylating agents may help restore their expression." (PMID 40917744, 2025).
Dent disease (4 papers, 2021 to 2024). Dent disease is a rare genetic renal tubular disease characterized by manifestations of proximal tubule dysfunction. "We also showed that megalin- and cubilin-mediated uptake of albumin is coordinately altered in our cell culture model of Dent disease." (PMID 38562767, 2024). "These include Dent disease (CLCN5, OCRL), AD tubulointerstitial kidney disease (ADTKD due to UMOD variants), nephronophthisis (TTC21B, NPHP4), Imerslund-Grasbeck syndrome 1 (CUBN) and papillorenal syndrome (PAX2)." (PMID 37578539, 2024). "The Renal proteinuria gene list corresponded to some genetic kidney diseases (CAKUT, tubulopathies, ciliopathies) that result in secondary FSGS such as Dent disease (CLCN5, OCRL), nephronophthisis (TTC21B, NPHP4), ADTKD-UMOD and Imerslund-Grasbeck syndrome 1 (CUBN)." (PMID 37578539, 2024).
diabetic nephropathy (4 papers, 2015 to 2024). "We propose that utilization of urinary cubilin shedding, as a urinary biomarker, will allow us to detect and intervene in diabetic nephropathy (DN) at an earlier stage." (PMID 26465605, 2015). "We hypothesize that perturbed insulin-Akt cascade in DM leads to alterations in trafficking of megalin and cubilin, which results in urinary cubilin shedding as a prelude to MA in early diabetic nephropathy." (PMID 26465605, 2015). "Countered diabetic nephropathy by inhibiting PKC-β, boosting PKA activities, and affecting the expression of re-absorption proteins megalin and cubilin." (PMID 38929190, 2024).
lupus (4 papers, 2007 to 2023). "Regarding the CUBN gene, variant rs1801238 was identified in two patients with RRMS and one with PPMS (from tow type‐B families); two of these patients (siblings) had an additional AID (hypothyroidism and systemic lupus erythematosus)." (PMID 30900415, 2019). "In conclusion, our results describe two main sub-populations of hypertrophic PECs in human glomeruli in proteinuric proliferative and non-proliferative human lupus kidney biopsies, both of which express megalin, cubilin, and ClC-5, components of the macromolecular complex normally expressed by PTCs." (PMID 37594671, 2023).
Stroke (4 papers, 2007 to 2025). Sudden impairment of blood flow to a part of the brain due to occlusion or rupture of an artery to the brain. "After excluding variants at the CUBN locus, known to alter ACR via effects on renal absorption, an ACR genetic risk score was associated with a higher risk of hypertension, and less strongly, type 2 diabetes and stroke." (PMID 31630189, 2019). "These alleles might have been expected to be benign on disease risk, but for individuals above the microalbuminuria threshold our results provide evidence of higher frequencies of T2D, coronary heart disease and stroke among CUBN allele carriers in contrast to non-carriers." (PMID 31630189, 2019).
type 2 diabetes (4 papers, 2019 to 2023). "In summary, we identified a rare coding CUBN variant implicated in elevated albuminuria levels, especially in individuals with type 2 diabetes." (PMID 30547231, 2019). "We hereby broadly examine the associations between four CUBN missense variants and eGFRcreatinine in Europeans with Type 1 (T1D) and Type 2 Diabetes (T2D)." (PMID 36926036, 2023). "In the combined meta-ExWAS of 33,985 Europeans (five discovery and 12 replication cohorts), we identified one novel CUBN variant associated with albuminuria levels and exerting >3.5-fold increased effects among individuals with type 2 diabetes compared with non-diabetic individuals." (PMID 30547231, 2019).
clear cell renal cell carcinoma (3 papers, 2019 to 2025). "Altered CUBN expression carries prognostic significance in carcinomas; loss of CUBN predicts worse outcomes in clear-cell renal cell carcinoma." (PMID 41374987, 2025). "Positive CUBN expression was associated with a better prognosis in clear cell renal cell carcinoma patients." (PMID 34326275, 2021). "Survival analysis of the cancer genome atlas (TCGA) dataset showed for the first time that low gene expression of MARC2, cubilin, and SLC47A1 and high gene expression of KRT17 are associated with poor overall survival in clear cell renal cell carcinoma patients." (PMID 31878355, 2019).
colorectal cancer (3 papers, 2022 to 2026). A primary or metastatic malignant neoplasm that affects the colon or rectum. "Furthermore, high CUBN expression has been associated with a worse prognosis (recurrence and survival) in patients with colorectal cancer." (PMID 41596244, 2026). "CUBN overexpression has also been linked to adverse prognosis in colorectal cancer." (PMID 41374987, 2025). "Its overexpression has been detected in samples from patients with colorectal cancer, with higher levels of CUBN in advanced stages." (PMID 41596244, 2026).
Fanconi syndrome (3 papers, 2017 to 2025). "Megalin-knockout mice and cubilin-deficient dogs demonstrate deficient endocytosis, reproducing low-molecular proteinuria and vitamin D deficiency, which are the main characteristics of human Fanconi syndrome." (PMID 28577559, 2017). "Megalin and cubilin have also been shown to be critical in Fanconi syndrome from other causes." (PMID 28577559, 2017). "We suppose that local inflammation may subsequently mediate brush border destruction, characterized by decreased megalin and cubilin expression, leading to the reabsorptive dysfunction of PTECs and Fanconi syndrome." (PMID 28577559, 2017). "As shown in semiquantitative analyses, the positive area staining ratio of megalin and cubilin in pSS patients with Fanconi syndrome was significantly lower than that in the control GML group (0.10 ± 0.01 vs 0.16 ± 0.02, p = 0.030; 0.05 ± 0.01 vs 0.11 ± 0.01, p = 0.004, respectively)." (PMID 28577559, 2017). "The innovation of our study is to show that defect endocytosis in PTECs mediated by megalin and cubilin may contribute to the reabsorption impairment in patients with pSS and Fanconi syndrome." (PMID 28577559, 2017). "Moreover, proteinuria occurring in patients with Fanconi syndrome can be explained by the lack of megalin and cubilin." (PMID 31737684, 2019).
gastric cancer (3 papers, 2021 to 2023). A primary or metastatic malignant neoplasm involving the stomach. "Some literature found that the CUBN and FLNC were associated with altered gastric cancer risk and involved the lymph node metastasis of gastric carcinoma, respectively." (PMID 37636564, 2023). "Survival analysis of subtype C2 shows that ABCA13, VPS13D, and CUBN affect the survival of gastric cancer." (PMID 34728653, 2021).
Hypertension (3 papers, 2014 to 2019). The presence of chronic increased pressure in the systemic arterial system. "In summary, our study showed that a long-term low salt intake attenuates hypertension progression in SHRs, prevents proteinuria with increase in cubilin expression and is associated with a modulation of the local kidney RAS toward renal protection." (PMID 26495970, 2015). "As such, the key alterations caused by sustained hypertension and hyperglycemia leading to NGAL urinary over-excretion must be looked for in tubular handling systems different from that of megalin/cubilin." (PMID 25148248, 2014).
nephrotic syndrome (3 papers, 2019 to 2021). A collection of symptoms that include severe edema, proteinuria, and hypoalbuminemia; it is indicative of renal dysfunction. "The loss of cubilin and megalin was not only found in nephrotic syndrome, but also in situations of mild renal injury." (PMID 32127613, 2020). "On this basis, it was recently hypothesised that the tubular proteinuria caused by cubilin deficiency could actually be protective against tubular overload, seen, for example, in nephrotic syndrome or even DKD." (PMID 30547231, 2019). "Moreover, Vitamin D major carrier, the D-binding protein (DBP), is less represented due to Nephrotic Syndrome (NS), proteinuria, and the alteration of the cubilin–megalin–amnionless receptor complex in the renal proximal tubule." (PMID 33671780, 2021).
renal carcinoma (3 papers, 2017 to 2023). A carcinoma arising from the epithelium of the renal parenchyma or the renal pelvis. "Interestingly, CUBN has been suggested as a predictive marker for the treatment of renal cancer patients with sunitinib and sorafenib." (PMID 31878355, 2019). "Immunohistochemistry and immunofluorescence analyses for ClC-5, megalin, cubilin, ANXA3, podocalyxin, CD24, CD44, HSA, and LTA marker were performed on 23 kidney biopsies from patients with Lupus Nephritis and 9 control biopsies (obtained from nephrectomies for renal cancer)." (PMID 37594671, 2023).
vitamin D deficiency (3 papers, 2019 to 2024). A nutritional condition produced by a deficiency of VITAMIN D in the diet, insufficient production of vitamin D in the skin, inadequate absorption of vitamin D from the diet, or abnormal conversion of vitamin D to its bioactive metabolites. "Additionally, LRP2 rs2075252 variant has been associated with vitamin D deficiency, while CUBN rs41301097 has been strongly correlated with higher 25(OH)D levels." (PMID 38008818, 2024). "This is the first study examining the potential implication of LRP2 and CUBN gene polymorphisms in OSAS occurrence, in association with vitamin D deficiency." (PMID 38008818, 2024).
Alport syndrome (2 papers, 2019 to 2022). A rare renal disease characterized by glomerular nephropathy with hematuria progressing to end-stage renal disease (ESRD), frequently associated with sensorineural deafness, and occasionally with ocular anomalies. "In a dog model of progressive Alport syndrome there was increased urinary excretion of megalin and cubilin associated with their reduced PT content." (PMID 35378997, 2022). "Increased urinary excretion of megalin and cubilin has been identified in models of Alport syndrome, in human diabetes mellitus, and in IgA nephritis." (PMID 35378997, 2022). "Some of the loci contain biologically plausible candidates in addition to the known CUBN (cubilin) locus: for example, rare mutations in COL4A4 (Collagen Type IV Alpha 4 Chain) cause Alport syndrome, a monogenic disease of basement membranes that frequently leads to end-stage kidney disease." (PMID 31511532, 2019).
anaemia (2 papers, 2018 to 2024). "Mutations in either cubilin (CUBN) or amnionless (AMN) genes cause Imerslund–Gräsbeck syndrome (IGS), a hereditary disease characterised by anaemia attributed to selective intestinal malabsorption of cobalamin and low-molecular weight proteinuria." (PMID 29402915, 2018).
End-Stage Renal Disease (2 papers, 2012 to 2021). "As genome-wide association studies identified cubilin gene CUBN as a locus for albuminuria, and urinary protein loss is a risk factor for progressive CKD, we tested the hypothesis that common genetic variants in CUBN are associated with end-stage renal disease (ESRD) and proteinuria." (PMID 22574174, 2012).
focal segmental glomerulosclerosis (2 papers, 2022 to 2023). A renal disorder characterized by sclerotic lesions in the glomeruli. "Here we present 3 patients with isolated proteinuria and focal segmental glomerulosclerosis (FSGS) caused by CUBN gene biallelic pathogenic variants." (PMID 34979989, 2022).
gallstones (2 papers, 2016 to 2024). Solid crystalline precipitates in the biliary tract, usually formed in the gallbladder, resulting in the condition of cholelithiasis. "The observed impact of serum cotinine on gallstone prevalence in this study may be associated with the FXR-megalin/cubilin signaling pathway." (PMID 39318386, 2024). "The FXR-megalin/cubilin signaling pathway plays a role in cholesterol balance regulation and participates in gallstone formation." (PMID 39318386, 2024).
multiple myeloma (2 papers, 2013 to 2017). "Like other members of the family, megalin is an endocytic receptor, and along with and sometimes in tandem with cubilin it binds a number of ligands including free light chains isolated and purified from the urine of patients with multiple myeloma." (PMID 23894629, 2013). "It has been shown that silencing megalin and cubilin genes may inhibit myeloma light chain uptake, suppressing inflammation in PTECs, and reducing the nephrotoxic effects." (PMID 28577559, 2017). "Myeloma light chains (LCs) are low-molecular weight proteins, relatively freely filtered in the glomeruli, endocytosed by a receptor-mediated process in the proximal tubule cells (PTCs) through the tandem endocytic receptors megalin/cubilin and targeted to degradative sites." (PMID 23894629, 2013).